IRF9 (interferon regulatory factor 9)
Diseases named in the same sentence as IRF9 in open-access papers (continued):
Sharing a sentence is not in itself a finding about the gene and the disease.
schizophrenia (1 paper, 2021). A major psychotic disorder characterized by abnormalities in the perception or expression of reality. "This suggests that in the chronic phase of schizophrenia, mRNA expressions of inflammatory mediators belonging to cluster 1 may be suppressed by the regulation of upstream transcription factors such as BCL6, RELA, and IRF9." (PMID 33815179, 2021).
Sepsis (1 paper, 2024). Sepsis is defined as life-threatening organ dysfunction caused by a dysregulated host response to infection. "Consequently, in-depth research is still required to validate these assumptions and disclose the underlying molecular mechanism of regulation of IRF9 on sepsis." (PMID 38894720, 2024). "In summary, we systematically identified 11 apoptosis-related differentially expressed genes in sepsis, and four hub genes (BCL2, FASLG, JAK3 and IRF9) were recognized as valuable diagnostic biomarkers." (PMID 38894720, 2024). "In the heart, IRF9 expression was upregulated in sepsis, while BCL2 was downregulated." (PMID 38894720, 2024). "BCL2, FASLG, IRF9 and JAK3 might be key regulatory genes affecting apoptosis in sepsis." (PMID 38894720, 2024).
uterine cancer (1 paper, 2016). Primary or metastatic malignant neoplasm involving the uterine corpus and/or the cervix. "Interestingly, overexpression of IRF9 in half of the breast and uterine cancer tumor was observed, indicating that IRF9 may be important in signaling transductions in these tumor types." (PMID 27421136, 2016).
vasculitis (1 paper, 2013). "Ifng also enhances expression of Irf1, Irf7, and Irf9, transcription factors that regulate the expression of immune-related genes that may also lead to severe inflammation of the arteries and subsequent lethal vasculitis." (PMID 24063402, 2013).
viral myocarditis (1 paper, 2025). Myocarditis that is caused by an infection with a viral agent. "Similarly, the μ2 protein of T1L reovirus contributes to viral myocarditis by suppressing IFN signaling through the induction of nuclear accumulation of IRF9." (PMID 40989773, 2025). "Additionally, the μ2 protein of T1L reovirus, which induces viral myocarditis, inhibits IFN signaling by promoting nuclear accumulation of IRF9." (PMID 40989773, 2025).
infection (80 papers, 2010 to 2026). The state of being infected such as from the introduction of a foreign agent such as serum, vaccine, antigenic substance or organism. "Presumably due to loss of IFN signaling during infection, the IRF9 knockout animals displayed dramatically increased sensitivity to infection as measured by increased morbidity and mortality." (PMID 37695101, 2023). "Under the experimental parameters of our infection experiments the increase in resistance produced by IRF9-deficiency was highly significant." (PMID 34237114, 2021). "While infection of IRF9-deficient mice with LCMV comes at the cost of persistent viral infection and inflammatory foci in kidney, liver and lungs, there is only minor tissue damage and mice recover from signs of disease by day 14 post-infection." (PMID 30791575, 2019). "In cattle, the antiviral activity of IRF7 and IRF9 has been reported to be associated with both Bovine Herpesvirus1 and Foot-and-Mouth Disease Virus infection." (PMID 27806696, 2016). "There were statistically significant associations between positive infection status and four of the five genes: IRF-9 (OR = 1.750, 95% CI = 1.16–2.638), ITGAM (OR = 1.533, 95% CI = 1.047–2.244), PSTPIP2 (OR = 2.191, 95% CI = 1.293–3.711), and RUNX1 (OR = 1.974, 95% CI = 1.069–3.646)." (PMID 36900096, 2023). "Metabolic differences between Irf9-/- and Ifnar1-/- mice may underlie the different susceptibility of these mice against lethal infection with L. monocytogenes." (PMID 34237114, 2021). "On the other hand, infection (the SFV group) significantly upregulated M1-linked TFs Stat1, Irf9 and Klf6 expression, as well as M2-linked Stat3 expression." (PMID 40547518, 2025). "We observed that the knockdown of LINC2781 significantly reduced the expression of STAT1/p-STAT1 and the downstream JAK-STAT pathway IRF9 protein in CVB5-infected cells after 24 h post-infection." (PMID 40626722, 2025). "The PRV UL41 protein, as well as the mRNAs of JAK1, Tyk2, STAT1, STAT2, and IRF9, were detectable in the RIP mixture, signifying that the mRNAs of JAK1, Tyk2, STAT1, STAT2, and IRF9 are among the targets of PRV UL41 during infection." (PMID 41341288, 2025). "In the universally upregulated gene module (darkorange) post-infection, the transcription factor IRF9 was central." (PMID 38743760, 2024). "In keeping with these data, we identified the transcription factors (TF) Stat2, Irf9 and Irf8 to be upregulated in NK cells infected with VACV, these TFs are associated with NK maturation and proliferation in response to infection." (PMID 36911702, 2023). "IRF3 and IRF9 expression remained low and generally equivalent between the two cell types during infection." (PMID 35085371, 2022). "Accordingly, the quantification of nuclear IRF9, pSTAT1, and pSTAT2 during infection with both virulent and attenuated ASFV stains showed a slight but significant decrease in cells treated at 8 hpi, and a more dramatic drop at 16 hpi." (PMID 34512601, 2021). "To assess the contribution of IFN-I and IRF9 to the cytotoxic effect of infection and liver damage, we measured serum levels of alanine aminotranferase (ALT)." (PMID 34237114, 2021). "Irf1, Irf7, Irf8, and Irf9 transcripts were significantly induced by infection in Ifnar1-/- mice, whereas Irf6 transcripts (abundant in uninfected mice) were significantly down-regulated." (PMID 34591933, 2021). "The modules that were co-up-regulated in CD4 and CD8 cells after infection included IRF9, IRF7, PLCB3, CXCL3, and TXN, among others." (PMID 34603402, 2021). "Both IRF9 and IFNAR1 deficiency alter liver and macrophage metabolism during infection, but in some cases their impacts differ." (PMID 34237114, 2021). "Next, we generated two different short hairpin RNA plasmids to knockdown IRF9 (shIRF9-1 and shIRF9-2) and tested the expression level of IRF9 in primary RPASMCs after infection with lentiviruses." (PMID 34925032, 2021).
infection (continued). "The region on SSC 7 (74 Mb) harbors the T-cell receptor alpha locus (TCRA), interferon-stimulated transcription factor 3 gamma (IRF9), and ribonuclease RNase A family 4 (ANG) genes, which have previously been associated with APP natural infection." (PMID 33193739, 2020). "During early infection, L. major-infected DCs exhibited a distinct type-I IFN-associated transcriptomic signature, including the upregulation of IRF2, IRF9, STAT1/2, and IFNAR." (PMID 31608064, 2019). "To further evaluate the effect of IRF9 silencing on OAd replication, we measured viral titers upon combined IRF9 siRNA and OAdmCherry infection." (PMID 31100952, 2019). "Accordingly, IRF9-deficient mice behave similar to IFNAR-deficient mice and survive both IP and IC infection with LCMV-Arm." (PMID 30791575, 2019). "We observed a persistence of expression of both STAT1 and IRF9 during the chronic phase of infection, albeit at lower levels." (PMID 29324751, 2018). "In order to activate transcriptional factors involved in innate immune responses, HeLa cells were pre-treated with recombinant human IFN-α, which activates STAT1, STAT2, and IRF9, followed by infection with WT-Ad." (PMID 26814140, 2016). "To further assess the functional implications of our observations in the acquisition of innate effector functions in the context of acute Listeria monocytogenes (LM) infection, we analysed IFNγ expression in WT and IRF9−/− mice 16 h post infection." (PMID 25953241, 2015). "WT/IRF9 mixed bone marrow chimera experiments confirmed the T-cell intrinsic role of IRF9 in the induction of Eomes expression in OVA-specific CD8+ T cells upon ΔactA rLmOVA infection." (PMID 25953241, 2015). "To show definitively that IFNα/β production by the tumour or the stroma was not involved in mediating the in vivo resistance to MYXV, we reduced K1492's ability to respond to IFNα/β by silencing IRF9 with a shRNA construct transduced via lentiviral infection." (PMID 23762429, 2013). "The replication of PIV3 (a negative ssRNA virus) was also inhibited significantly by high levels of U-STAT1/U-STAT2/IRF9, by >10-fold 48 h after infection (P<0.01)." (PMID 24065129, 2013). "Interestingly, we observed the downregulation of genes such as Tnf-α, Il18, Mx1, Rig1, Pkr, Stat1, Stat2 and Irf9, which appear to be hallmarks of hRSV persistence in contrast to the acute infection." (PMID 39296294, 2024). "In the IFE cells, infection was associated with the upregulation of interferon regulatory and inducible genes (IRF, IRF9, IFIT5, IFIH1), while a downregulation of IFI35 and IFI6 was observed, potentially indicating a mechanism to prevent excessive immune activation." (PMID 38743760, 2024). "Notably, the role of each of the five genes (ITGAM, IRF-9, LY6E, PSTPIP2, and RUNX1) has been linked to response to infection in the literature." (PMID 36900096, 2023). "During E30 infection, genes associated with the type I IFN signaling pathway (Isg15, Mx1, Mx2, Sp100, Ifit1, Ifit3, Ifih1, Irf7, Irf9, guanylate-binding proteins 2 [Gbp2], and Stat1) and defense response to viruses (Ddx58, Ddx60, Zbp1, Oas2, Nlrc5, and Eif2ak2) were significantly upregulated." (PMID 36147849, 2022). "Furthermore, we noted that STAT1, STAT2, IRF9 also exhibited high levels of transcription earlier in HuB20 infection than SY18." (PMID 36544767, 2022). "As the RNAseq data showed enrichment of FA metabolism genes in both Irf9-/- and Ifnar1-/- livers during infection, we compared FA levels in more detail by hypothesis testing." (PMID 34237114, 2021). "However, in both Irf9-/- and Ifnar1-/- livers the KB acetoacetate and hydroxybutyric acid were decreased three days post-infection." (PMID 34237114, 2021).
infection (continued). "Additionally, we detected an increase in free carnitine levels upon infection that was less pronounced in the knockouts, particularly in Irf9-/-." (PMID 34237114, 2021). "Despite having observed that the induction of Irf9 was greater in the Ifnar1-/- compared to the WT following infection in all three tissues, the final expression values of Irf9 remained lower in the Ifnar1-/- mice following infection than that observed in WT mice even before infection." (PMID 26918359, 2016). "We could demonstrate that Eomes expression was decreased in antigen-specific CD8+ T cells from IRF9−/− mice during the effector phase (day 7 post infection) and the memory phase (days 35–70)." (PMID 25953241, 2015). "Similarly, expression of several genes in the canonical IFN signaling pathway, including Ifng, Jak2, Stat1, Stat2, Socs1, Irf1, Irf9, Tap1, Ifitm1, Psmb8, Ifi35, Gas1 and Fit3 were up-regulated during infection by the mutant strain." (PMID 25201772, 2014). "Genes linked to STAT3 during infection were associated with GO terms such as regulation of cell proliferation (CCND1, JUNB), negative regulation of apoptosis (MCL-1, NFKB1), cytokine-mediated signaling pathway (IL10RA, SOCS1), and immune system process (CRK, IRF9)." (PMID 41115066, 2025). "This, together with the liver being a main target organ of L. monocytogenes infection, prompted us to investigate whether and how infection of wt, Irf9-/- or Ifnar1-/- mice changed hepatocyte transcriptomes and, particularly, genes related to metabolic pathways." (PMID 34237114, 2021). "Interestingly, before infection, the expression levels of many of these master regulators (e.g., REL, NFKB1, RELB, IRF2, IRF9) were different across the three species, while post-infection, their expression converged to practically the same level, regardless of species." (PMID 21187902, 2010). "Compared with ASFV-Δ4R infection, ASFV-WT infection consistently decreased the binding of STAT1, STAT2 and IRF9." (PMID 40618140, 2025). "Consistently, compared with infection with ASFV-WT, infection with ASFV-Δ4R increased nuclear translocations of phosphorylated STAT1, phosphorylated STAT2, and IRF9 in PAMs." (PMID 40618140, 2025). "Intriguingly, in H1299 cells, IRF9 and STAT2 expression was significantly reduced under both treatments when E1B-55K was present during infection." (PMID 41183090, 2025). "Strikingly, when comparing gene sets in Irf9-/- or Ifnar1-/- with wt after infection, we identified OXPHOS and FA metabolism gene enrichment in Irf9-/- and Ifnar1-/-." (PMID 34237114, 2021). "Other immune regulatory molecules, such as CD14 and CSF2, were significantly up‐regulated, while others, such as TLR4, IRF9 and CD36, were significantly down‐regulated after infection with H37Rv." (PMID 34632719, 2021). "Host genes commonly upregulated upon infection with either Ot strain include IFNB1 (interferon beta) and genes involved in regulating the type-I interferon response: IRF9 (interferon-regulated factor 9) and STAT1/2." (PMID 32620750, 2020). "In the present study, we tested the effect of ncpBVDV infection and IFNT challenge on the expression of IRF7 and IRF9 mRNA." (PMID 31861316, 2019). "Consistent with our initial observations, MCF7/pR cells displayed low levels of endogenous IRF9 compared to MCF7/pS cells, which were reduced further after OAdmCherry infection." (PMID 31100952, 2019). "The replication of encephalomyocarditis virus (EMCV, a positive ssRNA virus) was also inhibited, five-fold by high levels of wild-type STAT1/STAT2/IRF9 or four-fold by Y701F-STAT1/STAT2/IRF9, when assayed 6 h after infection." (PMID 24065129, 2013). "High levels of U-STAT1/U-STAT2/IRF9 also inhibited significantly the replication of YFV (a positive ssRNA virus), by 30% 48 h after infection with 100 MOI of virus (P<0.01)." (PMID 24065129, 2013).
infection (continued). "By 72 h post-infection, although only five common genes (IFI44, OASL, OAS3, IRF9, IRF7) are identified, these genes contribute significantly to a range of crucial GO processes, emphasizing the depth of the immune response despite the limited number of genes involved." (PMID 38957806, 2024). "Pretreatment with IFN-α2B for 16 hours before HSV-1 infection significantly decreased viral replication levels relative to untreated cells 72 hours after infection in healthy control cells, but not in STAT2-, IFNAR1-, STAT1-, and IRF9-deficient cells." (PMID 36976641, 2023). "IRF-9 (OR = 1.750, 95% CI = 1.16 to 2.638), ITGAM (OR = 1.533, 95% CI = 1.047 to 2.244), PSTPIP2 (OR = 2.191, 95% CI = 1.293 to 3.711), and RUNX1 (OR = 1.974, 95% CI = 1.069 to 3.646) had a significant expression with positive infection status." (PMID 36900096, 2023). "Other experiments have shown that IRF7 and IRF9 are upregulated in SARS-CoV-2 infection and that severe viral load may overwhelm the IFN response and determine the outcome of the infection, manifesting as a dysregulated IFN response." (PMID 36091053, 2022). "The transcriptions of IRF9 and STAT1 were increased markedly in the late stage of FJzz1 infection and the promotion of the phosphorylation and nuclear translocation of STAT1, implicating the activation of the JAK-STAT signaling pathway during FJzz1 infection." (PMID 35958569, 2022). "IRF7 and IRF9 are upregulated in SARS-CoV-2 infection and severe viral load may overwhelm the IFN response and determine the outcome of the infection." (PMID 36091053, 2022). "A significant endogenous IRF9 degradation was observed in PAM cells infected with ASFV at a multiplicity of infection (MOI) of 0.5 for 24 h in the presence or absence of IFN-α." (PMID 35972295, 2022). "Furthermore, a gradual up-regulation of IRF7, IRF9, STAT1 and STAT2 genes was observed in Calu-3 cells after the infection with SARS-CoV-2 for 24 h." (PMID 34578229, 2021). "Unexpectedly, this difference in survival rates between Irf9-/- and Ifnar1-/- mice was not reflected by the bacterial load of the liver and spleen three days post-infection." (PMID 34237114, 2021). "Consistent with the microarray, protein levels of GBP2 and GBP5 were reduced in the Ifnar1−/−, Irf9−/−, Irf1−/−, Trif−/−, and Irf3−/−Irf7−/− macrophages that undergo extensive cell-cell fusion during infection but not in Myd88−/−." (PMID 32150572, 2020). "We examined IRF9 expression following OAdmCherry infection and found a significant drop in IRF9 levels in MCF7/pS and 231/pS cells in the absence of palbociclib." (PMID 31100952, 2019). "Analysis of 231/pR cells revealed that OAdmCherry infection in the presence or absence of palbociclib results in a small increase in IRF9 expression." (PMID 31100952, 2019). "Of the interferon regulatory factor (IRF) genes annotated in KEGG, expression of IRF7 was significantly upregulated, and interestingly, all downstream transcriptional targets of IRF9 annotated in KEGG (MX1, OAS genes, ADAR, and PML) were consistently upregulated during acute infection." (PMID 30150281, 2018). "In summary, our results show that increased levels of U-STAT1, U-STAT2, and IRF9 are able to inhibit infection by several different RNA viruses without IFN treatment." (PMID 24065129, 2013). "In addition to IFNAR1, we have also shown the importance of IRF9, a component of the IFN-I-induced signalling complex interferon-stimulated gene factor 3 (ISGF3), in functional T cell responses in LCMV-Arm-infection, with both IFNAR1 and IRF9 independently required in a CD8+ T cell-extrinsic manner." (PMID 38543756, 2024).